PUM2 (pumilio RNA binding family member 2)
Description:
Sequence-specific RNA-binding protein that acts as a post-transcriptional repressor by binding the 3'-UTR of mRNA targets. Binds to an RNA consensus sequence, the Pumilio Response Element (PRE), 5'-UGUANAUA-3', that is related to the Nanos Response Element (NRE) (, PubMed:21397187). Mediates post-transcriptional repression of transcripts via different mechanisms: acts via direct recruitment of the CCR4-POP2-NOT deadenylase leading to translational inhibition and mRNA degradation. Also mediates deadenylation-independent repression by promoting accessibility of miRNAs. Acts as a post-transcriptional repressor of E2F3 mRNAs by binding to its 3'-UTR and facilitating miRNA regulation. Plays a role in cytoplasmic sensing of viral infection. Represses a program of genes necessary to maintain genomic stability such as key mitotic, DNA repair and DNA replication factors. Its ability to repress those target mRNAs is regulated by the lncRNA NORAD (non-coding RNA activated by DNA damage) which, due to its high abundance and multitude of PUMILIO binding sites, is able to sequester a significant fraction of PUM1 and PUM2 in the cytoplasm. May regulate DCUN1D3 mRNA levels. May support proliferation and self-renewal of stem cells. Binds specifically to miRNA MIR199A precursor, with PUM1, regulates miRNA MIR199A expression at a postranscriptional level.
Synonyms: KIAA0235; PUMH2; PUML2
Tractability: PROTAC: ubiquitination databases record sites on it; its protein half-life has been measured.
Gene: Protein-coding gene on chromosome 2 (20,248,691 to 20,352,234, reverse strand). Ensembl gene ENSG00000055917.
Subcellular location: Cytoplasm; Cytoplasmic granule; Cytoplasm, perinuclear region
Subcellular location (Human Protein Atlas): Cytosol
Pathways (Reactome):
Metabolism of proteins: Neddylation
Gene Ontology:
Molecular function: miRNA binding; mRNA 3'-UTR binding; protein binding; RNA binding
Biological process: miRNA processing; positive regulation of miRNA-mediated gene silencing; positive regulation of RIG-I signaling pathway; post-transcriptional regulation of gene expression; regulation of chromosome segregation; regulation of mRNA stability; 3'-UTR-mediated mRNA destabilization; regulation of miRNA-mediated gene silencing; negative regulation of gene expression; positive regulation of sprouting of injured axon; regulation of intracellular mRNA localization; regulation of postsynapse assembly; regulation of translation
Cellular component: cytoplasmic stress granule; cytosol; perinuclear region of cytoplasm; cytoplasm; glutamatergic synapse; neuronal cell body; postsynapse
Genetic constraint (gnomAD): Loss-of-function variants: 56 observed, 121.47 expected, observed/expected ratio (o/e) 0.46, 90% interval 0.37 to 0.58. The upper end of that interval is the gene's LOEUF score, 0.58, which puts it in group 2 of 6, group 1 being the genes least tolerant of losing a copy. Missense variants: 1,050 observed, 1,324.9 expected, observed/expected ratio (o/e) 0.79, 90% interval 0.75 to 0.83. Synonymous variants: 453 observed, 460.75 expected, observed/expected ratio (o/e) 0.98, 90% interval 0.91 to 1.06.
Homologues: Orthologues: chimpanzee PUM2 (99% identical), dog PUM2 (99% identical), pig PUM2 (99% identical), rabbit PUM2 (99% identical), macaque PUM2 (98% identical), guinea pig PUM2 (98% identical), rat Pum2 (98% identical), mouse Pum2 (98% identical), tropical clawed frog pum2 (85% identical), zebrafish pum2 (78% identical), Drosophila melanogaster pum (47% identical), Caenorhabditis elegans puf-9 (28% identical), and 7 more. Paralogues in human: PUM1 (78% identical).
Diseases named in the same sentence as PUM2 in open-access papers:
PUM2 is named in the same sentence as 59 diseases in open-access papers, as found by Europe PMC text mining. Sharing a sentence is not in itself a finding about the gene and the disease. The quoted sentences say what the papers report.
breast carcinoma (8 papers, 2020 to 2025). "Among other RBPs such as Elav-like (Elavl) proteins, Staufen1, and RNA binding protein fox-1 homolog 2 (Rbfox2), we found the Pumilio protein family consisting of Pum1 and Pum2 to be highly expressed in glioblastoma, neuroblastoma, and breast cancer cells." (PMID 34445704, 2021). "Assessment of the mRNA expression in breast cancer cells after PUM2 overexpression showed that the expression of INSM1 was downregulated more significantly by PUM2 overexpression." (PMID 32670859, 2020). "Silencing SCAMP1-TV2 inhibits the malignant biological behaviors of breast cancer cells by reducing its binding to PUM2 and further increasing the binding of PUM2 to INSM1 mRNA." (PMID 32670859, 2020). "As compared to the PUM2-NC+ INSM1-NC group, the viability, migration, and invasion of breast cancer cells were decreased in the PUM2+INSM1-NC group, but the apoptosis rate was increased; the contrary results were found in PUM2–NC+INSM1 group." (PMID 32670859, 2020). "The high expression of PUM2 in breast cancer tissues is inversely related to the overall survival and recurrence‐free survival of breast cancer patients." (PMID 32997416, 2020). "The mRNA expression of PUM2 was also significantly decreased in breast cancer tissues of luminal A type and triple negative type compared to paracancerous tissues." (PMID 32670859, 2020). "The inhibitory effects of PUM2 overexpression on the malignant biological behaviors of breast cancer cells was reversed by INSM1 overexpression." (PMID 32670859, 2020). "PUM2 overexpression inhibited the proliferation, migration, and invasion of breast cancer cells, as well as promoted the apoptosis." (PMID 32670859, 2020). "In order to further determine the role of SCAMP1-TV2 and PUM2 in breast cancer in vivo, the xenograft tumor experiment was performed on the nude mice." (PMID 32670859, 2020). "As well, Pum2 regulated the stemness of breast cancer cells via binding with miR-376a." (PMID 33999859, 2021). "This showed that PUM2 serves as a tumor suppresser in breast cancer." (PMID 32670859, 2020). "Therefore, we first detected the expression of PUM2 in breast cancer tissues and cells." (PMID 32670859, 2020). "Depletion of SCAMP1-TV2 reduced its interaction with PUM2 and enhanced the PUM2 and INSM1 interactions, leading to INSM1 mRNA degradation in breast cancer." (PMID 35992869, 2022). "In this study, the endogenous expression of SCAMP1-TV2, PUM2, and INSM1 in breast cancer tissues and cells was determined." (PMID 32670859, 2020). "In this study, PUM2 expression was significantly decreased in breast cancer tissues and expressed at a markedly low level in the MCF-7 and MDA-MB-231 breast cancer cells." (PMID 32670859, 2020). "Additionally, when grouping patients by subtype and using each gene list as a signature for KM analysis, NANOS1-, PUM2-, and CPSF4-responsive genes stratified DMFS for patients with the HER2-enriched subtype of breast cancer." (PMID 38410477, 2024). "Additionally, using each gene list as a signature for KM analysis revealed that Nanos1-, Pum2-, and Cpsf4-responsive genes stratify DMFS for patients with the HER2-enriched subtype of breast cancer." (PMID 39390150, 2024). "Indeed, Kaplan–Meier (KM) analysis of breast cancer patients, using median expression of NANOS1, PUM2, AND CPFS4 as a signature, revealed significant stratification of distant metastasis-free survival (DMFS) in patients with the basal subtype." (PMID 39390150, 2024). "Based on these findings, we hypothesized that NANOS1, PUM2, and CPSF4 may also serve as metastasis modifiers in breast cancer cells." (PMID 38410477, 2024). "Based on these findings, we hypothesized that the direct regulation of the Smarcd1 transcript by NANOS1, PUM2, and CPSF4 may be necessary for the metastasis of breast cancer cells." (PMID 38410477, 2024).
breast carcinoma (continued). "Indeed, Kaplan-Meier (KM) analysis of breast cancer patients grouped by subtype and using median expression of NANOS1, PUM2, AND CPFS4 as a signature, revealed significant stratification of distant metastasis-free survival (DMFS) in patients with the basal subtype." (PMID 38410477, 2024). "However, the expression and role played by PUM2 in breast cancer have not yet been reported." (PMID 32670859, 2020).
epilepsy (7 papers, 2011 to 2024). A brain disorder characterized by episodes of abnormally increased neuronal discharge resulting in transient episodes of sensory or motor neurological dysfunction, or psychic dysfunction. "To investigate the effect of Pum2 knockdown on epilepsy risk-factor expression, we took advantage of an existing Pum2 GT mouse exhibiting reduced Pum2 expression levels." (PMID 29046322, 2017). "In the study presented here, we investigated the molecular mechanisms of Pum2-loss-induced spontaneous epileptic seizures and present the first evidence of how Pum2 deficiency might cause late-onset epilepsy in Pum2 gene-trap (Pum2 GT) mice." (PMID 29046322, 2017). "Reduced Pum2 function has been implicated in epilepsy in both rodents and humans, and altered cortical wiring in S1 during development might conceivably contribute to seizures due to perturbations of excitation/inhibition balance that propagate through the network." (PMID 35262486, 2022). "Apart from epilepsy, it is reasonable to hypothesize that alterations in PUM2 may be associated with certain neuropsychiatric disorders that are caused by disruption of excitatory synapse homeostasis, especially those specific to hyperactivity or neurodegeneration." (PMID 30181804, 2018). "We mainly selected genes that are associated either with epilepsy, including ion channels and synaptic genes, or with Pumilio-dependent translational regulation, including mouse orthologs of known Pumilio targets in Drosophila and potential mammalian Pum2 targets." (PMID 22016787, 2011). "Together, these findings suggest a role of Pum2 in the development and maintenance of epilepsy in adulthood that is, inter alia, mediated by altered neuronal inhibition." (PMID 29046322, 2017). "However, in another aspect, PUM2 has an effort to develop mammalian neural stem cells, epilepsy, and human germ cell progression, and accumulating evidence proving that PUM2 is correlated with cancer progression." (PMID 37426488, 2023). "However, the contribution of altered sensory system function to epilepsy remains unclear and seizures reported by others in Pum2 KO mice might very well have a completely different origin." (PMID 35262486, 2022). "Furthermore, Pum2 was reported to be downregulated in two epilepsy models in Drosophila." (PMID 29046322, 2017). "Thus, our results argue for a role of Pum2 in epileptogenesis and the maintenance of epilepsy." (PMID 29046322, 2017).
ovarian cancer (6 papers, 2020 to 2025). A primary or metastatic malignant neoplasm involving the ovary. "PUM2 was validated to be involved in the development of ovarian cancer, acute ischemic kidney injury and mature neurons." (PMID 35997855, 2023). "PUM2 exhibited higher activity in ovarian cancer cells, and targeting PUM2 has been identified as an effective way to reverse cisplatin resistance in OvC23." (PMID 36681772, 2023). "For instance, PUM2 modulates the resistance to cisplatin in ovarian cancer via regulating USP46 expression." (PMID 35997855, 2023).
cervical cancer (5 papers, 2020 to 2022). A primary or metastatic malignant neoplasm involving the cervix. "Reports show that RBM33 promotes the progression of gastric cancer by targeting miR-149 to regulate IL-6, and that the circular RNA of RBM33 is involved in the progression of cervical cancer by regulating the miR-758-3p/PUM2 axis." (PMID 35368875, 2022). "Furthermore, circRBM33 knockdown have been shown to regulate the miR-758-3p/PUM2 axis to inhibit tumor growth in vivo, suppress cervical cancer cell proliferation, migration, invasion, and glycolysis, and promote cervical cancer cell apoptosis in vitro." (PMID 35318311, 2022). "LncRNA TUG1 bound with Pum2 and then promoted cervical cancer progression." (PMID 33999859, 2021). "In cervical cancer, lncRNA TUG1 promotes the upregulation of PUM2 expression through interaction with PUM2, enhancing the proliferation and migration of cervical cancer cells." (PMID 32997416, 2020).
glioblastoma (4 papers, 2019 to 2021). The most malignant astrocytic tumor (WHO grade IV). "The expression of PUM2 was significantly increased in glioblastoma, and the downregulation of PUM2 can significantly inhibit the proliferation and migration of glioblastoma cells." (PMID 35087827, 2021). "Knockdown of PUM2 in glioblastoma cell lines suppresses tumor cell proliferation, migration and invasion." (PMID 30787206, 2019). "In this study, we demonstrate that PUM2 positively promotes glioblastoma cell proliferation and migration mainly by repressing the expression of tumor suppressor gene BTG1." (PMID 30787206, 2019). "Taken together, our findings suggest that glioblastoma cells acquire their malignant properties probably due to down regulation of BTG1 by PUM2." (PMID 30787206, 2019). "Based on these findings, we suspected PUM2 expression would be elevated in established glioblastoma cell lines." (PMID 30787206, 2019). "To further clarify PUM2’s role in the malignant behaviors of glioblastoma cells, we designed shRNA to knock down PUM2 expression in U-251MG and U-87MGcell lines." (PMID 30787206, 2019). "We then tested PUM2 protein expression in multiple glioblastoma cell lines, including U-87MG, U-T98G, U-251MG and A172." (PMID 30787206, 2019). "Luciferase activities were significantly higher in glioblastoma cells with PUM2 knockdown than in the control cells." (PMID 30787206, 2019). "Here, we investigated PUM2’s role in glioblastoma development and its relationship with the cell cycle regulator BTG1." (PMID 30787206, 2019). "Our previous results have shown that glioblastoma cells show substantially elevated PUM2 protein expression and knockdown of PUM2 suppresses glioblastoma cell proliferation and migration." (PMID 30787206, 2019). "More importantly, we identify PUM2 as one of the key regulators of BTG1 expression since knockdown of PUM2 in glioblastoma cells gives rise to increased expression of BTG1." (PMID 30787206, 2019). "Compared to control shRNA, PUM2 shRNA significantly reduced cell numbers over 5 days, indicating knocking down PUM2 suppressed glioblastoma proliferation." (PMID 30787206, 2019). "In this study, we demonstrate that expression of PUM2, an RNA binding protein and positive regulator of cell proliferation, is elevated in glioblastoma tumor tissues and cell lines." (PMID 30787206, 2019). "Our results suggest that PUM2 promote glioblastoma development via repressing BTG1 expression." (PMID 30787206, 2019). "PUM2 knockdown remarkably suppresses glioblastoma cell proliferation and migration." (PMID 30787206, 2019). "To test whether BTG1 is the critical mediator of PUM2 on glioblastoma development, we knocked down BTG1 in glioblastoma cells with PUM2 knocked down." (PMID 30787206, 2019). "Furthermore, PUM2 knockdown blocked almost 80% of glioblastoma cells from invading through the matrigel." (PMID 30787206, 2019). "Knockdown of PUM2 led to increased BTG1 protein expression in glioblastoma cells." (PMID 30787206, 2019). "To figure out whether PUM2 could also contributes to the metastatic ability of glioblastoma cells, we further tested the migration and invasion capabilities in PUM2 knockdown glioblastoma cells." (PMID 30787206, 2019). "Knockdown PUM2 reduced the viability of glioblastoma cells by 50%." (PMID 30787206, 2019). "PUM2 expression is elevated in glioblastoma tumor tissues as well as glioblastoma cell lines." (PMID 30787206, 2019). "To investigate whether PUM2 contributes to the malignant properties of glioblastoma, we first checked the expression level of PUM2 in both glioblastoma tumor tissues and cell lines." (PMID 30787206, 2019). "Interestingly, knockdown of BTG1 not only completely reverses the effect of PUM2 knockdown but seems to over restore the capability of proliferation in glioblastoma cell." (PMID 30787206, 2019). "Therefore, our results suggest that PUM2 probably contribute to the malignant properties of glioblastoma." (PMID 30787206, 2019).
glioblastoma (continued). "In addition, knockdown of BTG1 restored the capabilities of migration and invasion in glioblastoma cells with PUM2 knockdown." (PMID 30787206, 2019). "Furthermore, knockdown of BTG1 reverses the effect of PUM2 knockdown on glioblastoma cell proliferation and migration." (PMID 30787206, 2019). "Here we hypothesize that PUM2 promote glioblastoma development probably by negatively regulating BTG1 expression." (PMID 30787206, 2019). "Therefore, our results indicate that BTG1 is the critical target of PUM2 and its down regulation by PUM2 contributes to glioblastoma development." (PMID 30787206, 2019). "Taken together, our findings indicate that elevated PUM2 expression and subsequent down regulation of BTG1 is one of the molecular characteristics of glioblastoma, suggesting that PUM2 and its downstream cellular pathways can be a potential pharmacotherapeutic target." (PMID 30787206, 2019). "In addition, glioblastoma cells with PUM2 knockdown had one-fold higher BTG1 mRNA expression than the control cells." (PMID 30787206, 2019). "Interestingly, knockdown of PUM2 leads to increase of BTG1 expression in glioblastoma cells." (PMID 30787206, 2019). "Furthermore, PUM2 negatively regulates BTG1 expression in glioblastoma cells." (PMID 30787206, 2019). "Thus, our results indicate that PUM2 promotes glioblastoma cell migration and invasion." (PMID 30787206, 2019). "As expected, in comparison with non-glioblastoma NHA and HA cell lines, PUM2 expression level is 1.58 to 3.56 times higher in glioblastoma cells than control cells." (PMID 30787206, 2019). "Our results indicate that activities of PUM2 are critical molecular characteristics of glioblastoma cells and BTG1 is involved in PUM2 downstream cellular pathways, suggesting PUM2 and BTG1 can be the potential pharmacotherapeutic targets in treatment of glioblastoma." (PMID 30787206, 2019).
viral infection (4 papers, 2014 to 2022). "Many of them, such as WDR7, INPP5E, CDK13, VAPA, NAMPT and PUM2, are known to be involved in viral infection mechanisms, whether at the point of the viral entry into the cell or during viral replication." (PMID 35563619, 2022). "Viral infection induces the formation of avSGs, including conventional SG markers, RIG-I, MDA5, LGP2, PKR, OAS, RNase L, DHX36, TRIM25, PUM1 and PUM2, some of which are critical in sensing non-self viral RNA and triggering antiviral signaling." (PMID 25340845, 2014).
temporal lobe epilepsy (3 papers, 2017 to 2022). A localization-related (focal) form of epilepsy characterized by recurrent seizures that arise from foci within the temporal lobe, most commonly from its mesial aspect. "Importantly, transgenic mice with PUM2 knockout show prominent epileptiform activity, and patients with intractable temporal lobe epilepsy and mice with pilocarpine-induced seizures have decreased neuronal PUM2, possibly leading to further seizure susceptibility." (PMID 30181804, 2018). "First, a Pum2 knockout mouse exhibits spontaneous seizures and second, PUM2 expression is reduced in human patients suffering temporal lobe epilepsy (TLE)." (PMID 28067623, 2017). "This is because its homologue, PUM2, has been reported to be downregulated in humans suffering temporal lobe epilepsy." (PMID 28067623, 2017). "Interestingly, reduced PUM2 was found in the neocortex of patients with drug-refractory Temporal Lobe Epilepsy (TLE) as well rats given seizures through pilocarpine injections." (PMID 30181804, 2018).
Azoospermia (2 papers, 2008 to 2015). Absence of any measurable level of sperm,whereby spermatozoa cannot be observed even after centrifugation of the semen pellet. "PUM2 may have important roles in germ cell development because PUM2 physically interacts with DAZ (Deleted in azoospermia) protein, which is essential for germ cell development." (PMID 26459019, 2015).